USP1 (ubiquitin specific peptidase 1)
Diseases named in the same sentence as USP1 in open-access papers (continued):
Sharing a sentence is not in itself a finding about the gene and the disease.
cancer (continued). "Therefore, a better understanding of how USP1 regulates carcinogenesis could improve the prevention and treatment of cancer." (PMID 36352191, 2023). "Thus, catalytic inhibitors of USP1 (such as ML323) may be a means to induce additional replication stress in cancer cells via this ‘USP1-trapping’ mechanism." (PMID 35365626, 2022). "Overall, USP1 might be a promising therapeutic target in cancers." (PMID 35663242, 2022). "In addition, inhibition of USP1 has the potential to target a variety of cancers." (PMID 34149436, 2021). "For example, protein-protein interactions are increasingly regarded as promising therapeutic targets in cancer and thus, characterizing the molecular determinants of USP1/UAF1 interaction may be important to guide efforts aimed to disrupt this interaction with therapeutic purposes." (PMID 25744535, 2015). "Importantly, several inhibitors of the USP1/UAF1 complex have been recently shown to act synergistically with cisplatin in cancer-derived cell lines, suggesting that this complex may represent a valid therapeutic target in cancer." (PMID 25744535, 2015). "A second aspect about USP1 autocleavage that has not yet been investigated is the possibility that it could be altered by naturally occurring cancer-associated mutations." (PMID 25744535, 2015). "Importantly, USP1 expression is deregulated in certain types of human cancer, suggesting that USP1 could represent a valid target in cancer therapy." (PMID 23937906, 2013). "MAST kinase stability is also likely regulated by ubiquitination, as MAST1 was also shown to be protected by ubiquitin-specific peptidases (USPs), USP1/USP28, and provided cisplatin resistance to cancer cells." (PMID 41237908, 2025). "The deubiquitinating enzyme USP1:UAF1, a therapeutic target in cancer, normally removes ubiquitin from FANCD2 unless FANCI is also modified." (PMID 40447800, 2025). "KIF9-AS1 enhances cancer stemness and sorafenib resistance in HCC by promoting Ubiquitin-specific peptidase 1 (USP1)-mediated deubiquitination of short stature homeobox (SHOX2)." (PMID 41298358, 2025). "Furthermore, USP1 may contribute to cancer development and metastasis." (PMID 39735674, 2025). "Suppressing USP1 leads to the degradation of the ID1 transcription factor, crucial for cancer progression." (PMID 38534787, 2024). "USP1 is an oncogene that deubiquitinates and stabilizes c-MYC, thereby promoting cancer progression in vitro and in vivo." (PMID 39513905, 2024). "Multiple deubiquitinating enzymes, including USP1, USP7, and USP10, have been reported to play a regulatory role in the development of various cancers." (PMID 37821462, 2023). "In future studies, we will assess the pharmacological inhibition of USP1 and/or PARP1 as anti-cancer compounds for CCA." (PMID 37821462, 2023). "USP1 is a new DUB capable of stabilizing survivin, and USP1 depletion enhances TRAIL-mediated cancer cell death by degrading survivin." (PMID 36153316, 2022). "Our findings suggest that USP1 depletion destabilizes MAST1, which facilitates cisplatin sensitization in cancer." (PMID 35966591, 2022). "Thus, aberrant retention of USP1 molecule on DNA caused by combined SPRTN and USP1 catalytic inhibition may be effective in further enhancing cytotoxicity of cisplatin and other chemotherapeutics in a variety of cancer cells." (PMID 35365626, 2022). "We found that both USP1 and MAST1 are more highly expressed in cancer than in normal tissue, and we confirmed this observation by immunohistochemistry using human tissue samples." (PMID 35966591, 2022). "We further delineate the mechanism by which the depletion of USP1 downregulates MAST1-mediated activation of MEK1 and its downstream ERK1/2 in cancers." (PMID 35966591, 2022). "Drugs targeting USP1 and USP30 are in clinical development for cancer and kidney disease respectively." (PMID 35737447, 2022). "We further validated the correlation between USP1 and MAST1 protein in several cancer cell lines by Western blotting." (PMID 35966591, 2022).
cancer (continued). "Collectively, these results clinically validate our findings and support the positive correlation of USP1 and MAST1 across different cancer types." (PMID 35966591, 2022). "USP family members play different functions in cancer, and most of them, such as USP1, USP2, USP7, USP14, and USP17, contribute to cancer promotion." (PMID 33619866, 2021). "USP1 function as an oncogene by interacting with DNA repair signal through PCNA and FANCD2, USP4 promote cancer progression by deubiquitinating TRAF2 and TRAF6 and thereby regulating the TGFβ signaling pathway." (PMID 34545063, 2021). "Both the inhibition/degradation of USP1 and the increase in mono-ubiquitinated PCNA are new activities for PEITC that can explain the previously recognized ability of ITCs to enhance cancer cell sensitivity to cisplatin treatment." (PMID 28881649, 2017). "Several members of the DUB family are known to contribute to carcinogenesis, including USP1, USP2, USP7 and USP22, while other DUBs are down-regulated in human cancers, including USP10 and BAP1." (PMID 27030989, 2016). "USPs, such as USP1, USP2, USP7, USP9x and USP14, were recently shown to contribute to the development of cancer and are emerging as novel cancer drug targets." (PMID 27780924, 2016). "Overexpression of USP1 has been reported in osteosarcoma and non-small cell lung cancer (NSCLC), among other cancer types." (PMID 25744535, 2015). "This view has recently gained experimental support with the identification of two compounds that inhibit the activity of the USP1/UAF1 complex, and reverse the resistance of NSCLC cells to cisplatin, a DNA damaging drug commonly used in cancer chemotherapy." (PMID 23937906, 2013). "So, calycosin H10‐inhibited USP1 and USP22 should be promising targets to induce cancer cell death." (PMID 41541703, 2026). "In this work, we first disclosed the widely potent reversing effects of KSQ‐4279, a highly‐selective USP1 inhibitor currently in clinical trial (Phase I) for advanced solid tumors (NCT05240898), on ABCB1/ABCG2/ABCC1‐induced MDR cancers, and the exact mechanisms behind were elucidated." (PMID 41328326, 2025). "Overall, while targeting USP1 holds promise as a therapeutic strategy for SCLC, further research efforts are needed to fully comprehend their therapeutic potential and determine the optimal application in SCLC and other cancer types." (PMID 39735674, 2025). "Moreover, other pharmacological USP1 inhibitors induce DR5 mRNA expression through downregulation of miR-216a-5p, eventually increasing sensitivity to TRAIL in cancer." (PMID 36153316, 2022). "Indeed, a low-BCAA diet decreased the Usp1 protein level in PDAC generated by orthotopic transplantation, concomitantly with cancer cell proliferation arresting." (PMID 35663242, 2022). "In addition, we analyzed the protein levels of USP1 and RPS16 in two tissue arrays containing cancer tissues and adjacent normal tissues from 90 HCC patients (obtained from Shanghai Outdo Biotech Company)." (PMID 34154657, 2021). "USP1 and WDR48 function together in regulating cancer cell proliferation via the cell cycle." (PMID 32951278, 2020). "Noteworthily, CRCs at advanced stage (IV) showed elevated level of USP1, although it was statistically not significant due to the limited numbers of patients with stage IV cancers in the cohort." (PMID 31921663, 2019). "USP1 is a topical target for cancer therapeutics, particularly given its synthetic lethality with BRCA1, and it is possible that pharmacological inhibition of USP1 may lead to USP1 trapping in addition to abrogation of its DUB activity, and therefore may explain some of the effects seen." (PMID 38572758, 2024). "At present, studies on USP1 mainly focus on cancer and tumors, while its role in nonunion is still unknown." (PMID 36859264, 2023).
cancer (continued). "Besides OTUB1, other DUBs, such as USPs family (USP1, USP7, USP8, USP15, USP22), OTUs family (OTUD7B, OTUD6B, A20, and OTUB2) and other DUBs have been identified to regulate the progression of various cancers and applied for clinical cancer therapy." (PMID 35715413, 2022). "Likewise, several DUBs including DUB3, OTUB1, USP1, and USP27X have been reported to be capable of stabilizing Snail1 and promoting cancer progression, which also indicates the preference of Snail1 towards different DUBs within assorted cellular contexts and milieus." (PMID 32968046, 2020). "We also examined the expression of USP1 in CRC cell lines and primary tumors by using RT-qPCR, immunoblotting, and immunohistochemistry and found that the increased level of USP1 was correlated with short overall survival of patients and with advanced stages of cancers." (PMID 31921663, 2019). "As expected, compared with those in the USP1-KO group, the Kyoto Encyclopedia of Genes and Genomes (KEGG) analysis showed the enrichment of Wnt, Notch, and Hedgehog pathways, which play essential roles in cancer stem cell regulation and may support the survival of CTCs." (PMID 33102219, 2020). "Thus, we hypothesized that USP1 contributed to cancer metastasis mainly by promoting cancer cell survival in the blood rather than promoting cancer cell invasion." (PMID 33102219, 2020). "Combined treatment with a USP1 inhibitor, ML323, and TRAIL-induced apoptosis via survivin downregulation and DR5 upregulation in cancer cells but not in normal cells." (PMID 36153316, 2022).
tumor (65 papers, 2011 to 2026). "KSQ-4279 (RO7623066), the first oral USP1 inhibitor to enter clinical trials, shows high selectivity and robust efficacy, including tumor regression in HR-deficient and PARPi-resistant models; combination with olaparib is synergistic (NCT05240898)." (PMID 41190241, 2025). "Taken together, these results indicated that the high expression of USP1 was closely associated with tumour progression." (PMID 32951278, 2020). "We found that USP1 knockdown cells had a significant reduction in tumor growth compared to control cells, indicating that USP1 loss reduces cell growth both in vitro and in vivo." (PMID 33114077, 2020). "The UAF1/USP1 complex deubiquitinates a wide range of substrates and has been implicated in the regulation of DNA repair processes, tumor pathogenesis, and antiviral innate immunity." (PMID 33247121, 2020). "Similarly, USP1 is aberrantly overexpressed in various cancers and is closely associated with tumor development and progression, and is also generally upregulated in the BMCs of B-ALL patients." (PMID 41146039, 2025). "The molecular association of Mucin-5B and USP1 with NSCLC tumor status remains to be illustrated." (PMID 23284758, 2012). "Moreover, we found that USP1 deficiency inhibited tumor formation in vivo." (PMID 39513905, 2024). "Furthermore, we observed that USP1 deficiency inhibited tumor formation in vivo." (PMID 39513905, 2024). "In addition, USP1 mutations have been identified, albeit at a low frequency, in tumor samples." (PMID 25744535, 2015). "Inhibition of USP1 or its downstream signalling has been shown to sensitise HRD tumour cells to PARPis." (PMID 41537447, 2026). "Consistent with these in vitro findings, USP1 knockdown suppressed tumor growth in an intrathoracic xenograft model." (PMID 42069682, 2026). "USP1 is involved in various tumor-related activities, including controlling autophagy, developing chemotherapy resistance, promoting cell growth, and facilitating cellular movement." (PMID 39735674, 2025). "The potential of USP1 inhibitors lies in their ability to modulate the tumor microenvironment and enhance the efficacy of immunotherapeutics." (PMID 40001543, 2025). "Among these, ubiquitin-specific peptidase 1 (USP1) has garnered considerable interest because of its role in tumor development." (PMID 40136409, 2025). "Inhibition of USP1 was also demonstrated to significantly reduce tumor burden in a therapy-resistant DLBCL-engrafted PDX mouse model." (PMID 40001543, 2025). "It has been shown to inhibit the USP1/UAF1 complex and exhibit strong dose-dependent tumor response in xenograft-derived BRCA-mutated triple-negative breast cancer with synergy seen when given with a PARP inhibitor." (PMID 40001543, 2025). "To determine USP1 expression in normal and tumor tissue samples, we analyzed the mRNA and protein levels of USP1 from The Cancer Genome Atlas and Clinical Proteomic Tumor Analysis Consortium dataset using GEPIA and UALCAN." (PMID 39814232, 2025). "Recently, various novel inhibitors of USP1 with satisfactory anti-tumor benefits have been developed to induce ID1 degradation, cellular differentiation, and apoptosis in leukemic cells." (PMID 41146039, 2025). "Functionally, TAZ overexpression partially reverses the anti-tumor effects of USP1 knockdown or ML323 (a selective inhibitor of USP1) treatment." (PMID 39062505, 2024). "In summary, our results showed that USP1 deficiency downregulated c-MYC, which promoted tumor growth in vivo." (PMID 39513905, 2024). "We also indicate that TAZ partially accounts for the tumor effect of USP1 overexpression by constructing Flag, Flag-USP1 and Flag-USP1 + shTAZ stably HLF cell line." (PMID 37041150, 2023). "Twelve of the ninety-nine DUB genes were identified as differentially expressed in MB compared to non-tumor tissue (p < 0.0001) for the GO category of DNA repair in the Swartling dataset, including USP1, OTUB1, UCHL5, USP7, and PSMD14 (aka POH1)." (PMID 37892185, 2023).
tumor (continued). "The xenograft mouse model used to study the effects of USP1 in vivo confirmed that silencing USP1 in HLF cells inhibited tumor growth in vivo." (PMID 37041150, 2023). "USP1 can stabilize the snail protein and induce chemotherapy resistance in platinum-resistant tumor models." (PMID 37041150, 2023). "As a pivotal member of the deubiquitinating enzyme family, USP1 exerts regulatory effects on various oncological biological processes, including tumor proliferation, drug resistance, and metastasis." (PMID 37821462, 2023). "Targeting USP1 by shRNA or pimozide significantly reduced tumor burden of a mouse model established with engraftment of rituximab/chemotherapy resistant DLBCL cells." (PMID 36352191, 2023). "The tumor weight of the mice in USP1 knockdown group was significantly lower than that of the control mice." (PMID 36352191, 2023). "To validate the clinical relevance of USP1 expression in patients with RCC (n = 40), we performed immunoblotting to analyze the expression levels of USP1 in a panel of non-tumor and tumor tissues." (PMID 36153316, 2022). "Nonetheless, our data suggests that USP1 is a novel target for MYC-driven tumours and that this warrants further investigation." (PMID 36240066, 2022). "To determine the potential mechanism of ML-323, we embedded the dissected tumor to synthesize a tissue chip accordingly and verified the related proteins (USP1 and Ki 67) by IHC." (PMID 36357365, 2022). "We detected USP1 expression in the tumor and adjacent tissues of patients with HCC using immunohistochemical staining." (PMID 36357365, 2022). "In RCC, USP1 and survivin were highly expressed in tumor tissues compared to normal tissues, thereby indicating a positive correlation and poor prognosis." (PMID 36153316, 2022). "USP1 was found to be up-regulated in BRCA1 mutant tumours where it appears to stabilise and protect the replication fork, thereby promoting survival in these cells with on-going DNA damage due to BRCA1 loss or mutation." (PMID 36240066, 2022). "To analyze the influence of USP1 on MAST1-mediated development of cisplatin-resistance during tumor progression, we performed several assays related to carcinogenesis." (PMID 35966591, 2022). "Further, ML323 targets USP1, thereby inhibiting the proliferation of OV cells by blocking the progression of the OV cell cycle, thus achieving inhibition of tumor proliferation." (PMID 35923700, 2022). "In this study, we found high USP1 expression in tumor tissues and that it correlated with poor prognosis in RCC." (PMID 36153316, 2022). "This study aimed to investigate the expression and role of USP1 in HCC using tumor and adjacent tissues of patients with HCC." (PMID 36357365, 2022). "In fact, compared with xenografts stably expressing control shRNA, xenografts stably expressing USP1 shRNA had significantly reduced tumor size and weight." (PMID 34154657, 2021). "A previous study showed that miR‐194‐5p was a target of circ‐USP1 and both were involved in regulating the permeability of the blood‐tumour barrier." (PMID 33484504, 2021). "Regarding the growth of OS primary tumor, USP1, USP22 and USP39 have been shown to participate in the control of OS cell proliferation." (PMID 34571917, 2021). "These animal studies established the role of USP1 in promoting tumor growth and proliferation in HCC cells." (PMID 34154657, 2021). "Considering the importance of USP1 in regulating DNA repair, it has long been considered a potential therapeutic target for tumours." (PMID 32951278, 2020). "We found that USP1 expression had a slightly positive correlation with tumour purity (R = 0.106, P = 4.98E‐02)." (PMID 32951278, 2020). "After 5 weeks of liver xenografting, the USP1-KO group showed a lower tumor number than the USP1-NC group (P < 0.05)." (PMID 33102219, 2020). "Since USP1 is known to act in an oncogenic manner while UCHL1 and UBL4A are shown to have tumor-suppressive functions, we focused our studies on how USP1 alters TAZ." (PMID 33114077, 2020).